ALB (albumin)
Diseases named in the same sentence as ALB in open-access papers (continued):
Sharing a sentence is not in itself a finding about the gene and the disease.
sarcopenia (continued). "Our study demonstrates that albumin levels are valuable not only in the diagnosis of sarcopenia but also in the evaluation of clinical outcomes." (PMID 40005385, 2025). "Nutritional status, assessed via serum albumin levels, was also identified as a significant predictor of sarcopenia." (PMID 40915183, 2025). "Significant correlations of several LFTs with muscle mass and presence of sarcopenia were observed, including especially cholinesterase (r = 0.35), albumin (r = 0.289) and creatinine (r = 0.342; all p < 0.01)." (PMID 40922637, 2025). "Regarding blood product usage, the MS group received less plasma than the control group, while the sarcopenia and combined groups required more albumin (P < 0.05)." (PMID 40730978, 2025). "Albumin is a potential biomarker of both frailty and sarcopenia, and frail patients have significantly lower albumin levels than their healthy peers, regardless of age." (PMID 40944175, 2025). "Albumin concentration was significantly lower in subjects with sarcopenia (p = 0.002), while CRP levels were significantly higher (p = 0.035), but still within the clinical reference ranges that do not indicate an acute inflammatory process (>5 mmol/L)." (PMID 40430249, 2025). "We constructed a sarcopenia prediction model with five variables: age, ALB level, BR MT, Glh MT, and CMMC." (PMID 39910436, 2025). "Lower BMI, lower serum ALB, FGF19, TNF-α, and higher circulating GDF11 are associated with sarcopenia." (PMID 40969368, 2025). "The nutritional and metabolic status of patients with CRLM, reflected in biomarkers such as serum albumin and sarcopenia, is a key determinant of systemic inflammation, physiological reserve, and treatment tolerance." (PMID 40805233, 2025). "Regarding laboratory information, patients with sarcopenia demonstrated lower levels of albumin, hemoglobin, and free triiodothyronine but higher levels of thyroid-stimulating hormone (all P<.05)." (PMID 40327860, 2025). "Both the muscle mass and albumin levels of older patients decreased significantly postCT, while the prevalence of sarcopenia increased considerably." (PMID 39941382, 2025). "We observed that albumin levels were significantly lower in sarcopenia and probable sarcopenia then non-sarcopenia." (PMID 41345186, 2025). "The Albi-Sarcopenia Score amalgamates the Albumin-Bilirubin (ALBI) grade, a reliable indicator of liver function, with sarcopenia, a condition characterized by the loss of skeletal muscle mass and function." (PMID 40287454, 2025). "Based on the results, six optimal predictors were identified: underweight, sarcopenia, poor performance status, midstream urine culture, urinary leukocyte count, and albumin-globulin ratio (AGR)." (PMID 40065041, 2025). "In male patients, those with sarcopenia were significantly older and had lower height, calf circumference, hemoglobin, albumin, and GNRI scores, as well as higher CRP levels compared with nonsarcopenic males." (PMID 41393007, 2025). "ALB dysfunction contributes to sarcopenia pathogenesis through impaired nutrient signaling and amplified oxidative stress." (PMID 40969368, 2025). "Univariate analysis (Cox proportional risk model) showed that sarcopenia, KPS score, albumin level, T stage, and N stage were correlated with patients’ OS." (PMID 40051963, 2025). "We assessed the relationship between nutritional markers such as albumin, prealbumin, retinol-binding protein, and sarcopenia in our study." (PMID 40740773, 2025). "Patients with sarcopenia showed lower body weight, BMI, and muscle mass (all p < 0.001); lower albumin levels (p = 0.002); and lower GNRI but higher GNRI nutritional risk (both p < 0.001)." (PMID 41169410, 2025). "The albumin bilirubin (ALBI) - sarcopenia score has shown superior effectiveness in comparison with MELD-sarcopenia in patients with HCC." (PMID 40273113, 2025).
sarcopenia (continued). "Hematological parameters indicate that sarcopenia patients commonly exhibit reduced albumin and hemoglobin levels, potentially reflecting alterations in muscle–liver metabolic interactions." (PMID 40507924, 2025). "Mean albumin in the sarcopenia group at the one-month follow-up and after a six-month follow-up was lower when compared to those in the no sarcopenia group and this was found to be statistically significant (p-value <0.001)." (PMID 40476129, 2025). "Multivariable analysis identified paravertebral muscle-defined sarcopenia (HR = 3.046, p = 0.029), platelet-to-neutrophil ratio, hemoglobin-albumin-lymphocyte-platelet score, tumor size, and N stage as independent prognostic factors." (PMID 41199827, 2025). "RF models determined the most important variables related to sarcopenia: albumin, C-reactive protein (CRP), vitamin D and folates." (PMID 40362666, 2025). "Sarcopenia and a high C-reactive protein-to-albumin ratio are independent prognostic factors in patients with pancreatic cancer after pancreaticoduodenectomy." (PMID 38913646, 2024). "Patients with sarcopenia were older, more likely to be male, had a lower BMI, and had lower albumin and hemoglobin levels." (PMID 38719903, 2024). "Significant differences in ECOG performance status (p = 0.001), SPMSQ score (p = 0.001), and serum albumin level (p = 0.001) were observed between the sarcopenia and non‐sarcopenia groups." (PMID 39104037, 2024). "The direction of the effect shows that higher age increases the likelihood of sarcopenia, while higher levels of albumin, adiponectin, and myostatin reduce its likelihood." (PMID 39125361, 2024). "The effect of sarcopenia is likely significantly weaker than the effects of other strong prognostic indicators, such as serum albumin." (PMID 39104037, 2024). "The albumin level in the sarcopenia group was 37.65 ± 2.83 g/L, which was significantly lower than that in the non-sarcopenia group (P < 0.001)." (PMID 38822297, 2024). "Previous studies have shown that sarcopenia is associated with decreases in nutritional indicators such as PNI, hemoglobin, prealbumin, and albumin." (PMID 39042270, 2024). "Patients with sarcopenia had significantly lower serum albumin levels at the time of admission (p < 0.001) than non-sarcopenic patients." (PMID 38892826, 2024). "Sarcopenia, albumin levels, and tumor staging were determined as essential factors predicting survival." (PMID 39026185, 2024). "Overall survival in the sarcopenia and high C-reactive protein-to-albumin ratio groups was significantly poorer than that in the non-sarcopenia and low C-reactive protein-to-albumin ratio and sarcopenia or high C-reactive protein-to-albumin ratio groups." (PMID 38913646, 2024). "In this study, we introduced the AHLC model, which integrates albumin, HDL cholesterol, lymphocytes, and calcium as key predictors of sarcopenia risk." (PMID 39726874, 2024). "Our study also showed that albumin level and inflammation markers (CRP and FC) were associated with sarcopenia in univariable analysis." (PMID 38438954, 2024). "In the unadjusted model, age, ASCVD, subjective global assessment score, body mass index, relative OH, serum albumin, creatinine, phosphorus, and log-transformed intact PTH levels were significantly associated with sarcopenia." (PMID 39478830, 2024). "In the unadjusted model, age, ASCVD, BMI, relative OH, SGA, serum albumin, creatinine, phosphorus, and log-transformed intact PTH levels were significantly associated with sarcopenia." (PMID 39478830, 2024). "The backward deletion of non-significant variables allowed us to build a final model, which includes age, albumin, adiponectin, and myostatin concentrations as variables of interest in predicting sarcopenia." (PMID 39125361, 2024). "Second, serum albumin was also suggested as a biomarker of frailty and sarcopenia and a simple indicator of undernutrition." (PMID 38792928, 2024).
sarcopenia (continued). "The authors showed that MSTN, together with albumin and creatine kinase, were complementary markers for the assessment of the presence of sarcopenia in these patients." (PMID 38542721, 2024). "The positive impact of the Ophiocephalus striatus extract treatment on IL-6 serum levels in older adults with sarcopenia is possible because of its high protein and albumin content." (PMID 38525752, 2024). "Our study, which was published in 2022, confirmed that patients with sarcopenia who underwent albumin-paclitaxel chemotherapy experienced a significant increase in the incidence of grade ≥ 3 neurotoxicity and neutropenia." (PMID 38746684, 2024). "Sarcopenia and preoperative plasma albumin < 3.5 g/dL were predictors for 90-day mortality (p = 0.004 and p > 0.001)." (PMID 39604574, 2024). "As revealed by univariable regression, sarcopenia (p < 0.001), albumin (p = 0.048), Child-Pugh score (p = 0.023), and NSBBs (p = 0.029) were considered potential 2-year rebleeding predictors." (PMID 38699840, 2024). "In meta-analysis, blood albumin levels were found among the elderly adults presenting with statistically significant sarcopenia." (PMID 39666645, 2024). "Sarcopenia, preoperative plasma albumin < 3.5 g/dL, and open and urgent surgery were significantly correlated with major complications (p = 0.015, p = 0.022, p = 0.003, and p < 0.001, respectively)." (PMID 39604574, 2024). "It is associated with persistent inflammation, decreased protein synthesis, and low albumin levels, as well as sarcopenia." (PMID 39595030, 2024). "In univariate logistic regression analysis, sex, age, BMI, albumin, hemoglobin, transferrin, serum iron, TIBC, and TSAT were significantly associated with the risk of sarcopenia." (PMID 38719903, 2024). "Sarcopenia (*P = 0.032), age > 65 years (**P = 0.003), albumin < 35 g/L (*P = 0.022), duration of surgery (*P = 0.019), and intraoperative bleeding volume (P < 0.001) were identified as factors associated with the occurrence of postoperative complications." (PMID 39725829, 2024). "-Walking exercise plus BCAAs significantly increased grip strength and SMI, reducing sarcopenia prevalence. -Albumin significantly increased in all groups." (PMID 40757549, 2024). "The importance of albumin serum concentration was also underscored by authors of an observational study on sarcopenia and frailty." (PMID 38674833, 2024). "The SMI and HGS were key elements for the diagnosis of sarcopenia, serum albumin reflected the nutritional status, and higher NLR indicated higher levels of systemic inflammation." (PMID 38445206, 2024). "Univariate analysis showed that albumin, the ALBI grade, AFP, up-to-seven criteria, and preoperative sarcopenia and myosteatosis were associated with OS (all p < 0.05)." (PMID 39456597, 2024). "Regarding laboratory data, patients with sarcopenia had lower serum albumin, creatinine, and phosphorus levels, but higher levels of intact PTH." (PMID 39478830, 2024). "In summary, sarcopenia was associated with age, ESR, RCP (positively) and BMI, Fe, Total Cholesterol, albumin (%) albumin (g), and gamma proteins (negatively)." (PMID 37960189, 2023). "Univariate or multivariate logistic regression analysis was performed to assess the association of albumin, GNRI, and CONUT with the diagnosis of sarcopenia." (PMID 36819693, 2023). "In terms of patient background, the sarcopenia group had a significantly lower proportion of women, BMI, and serum albumin levels among patients with CKD G3." (PMID 38068851, 2023). "For men, participants with sarcopenia had higher HbA1c levels, while lower prealbumin, albumin, UA and 25(OH) D3 levels." (PMID 36777353, 2023). "We found that being male was considered a risk factor for all the phenotypes, while a higher BMI was the most important protective factor for sarcopenia, sarcopenic obesity (along with Fe) and osteosarcopenia (along with albumin)." (PMID 37960189, 2023).
sarcopenia (continued). "In contrast, the serum level of albumin was lower (P = .047) in the sacropenia group compared with non-sarcopenia group." (PMID 37960747, 2023). "The present study examined the relationship between preoperative sarcopenia and albumin status, as well as postoperative survival outcomes in Japanese patients with nonmetastatic RCC who had nephrectomy." (PMID 37371699, 2023). "Although serum albumin can provide a benchmark for sarcopenia, blood tests are less likely to provide a prognostic value for FD." (PMID 37355574, 2023). "The resulting data of multivariate analysis determined that serum albumin, BMI, muscle wasting, and subjective overall patient scores were capable of independently predicting sarcopenia in individuals with colorectal cancer." (PMID 37965475, 2023). "Our study found an association between sarcopenia and certain inflammatory mediators as CRP, albumin, CRP/albumin ratio, IL-1β, and cfDNA." (PMID 37465171, 2023). "According to random forest analysis, a higher BMI was the most important protective factor for sarcopenia, for sarcopenic obesity (along with Iron) and for osteosarcopenia (along with albumin)." (PMID 37960189, 2023). "According to logistic regression analysis, sarcopenia was associated with age, erythrocyte sedimentation rate (ESR), C-reactive protein (CRP) (positively) and BMI, Iron (Fe), Total Cholesterol, albumin (%), albumin (g), and gamma proteins (negatively)." (PMID 37960189, 2023). "Patients with sarcopenia necessitated more intraoperative transfusions, had lower albumin levels, and had prolonged hospital stays." (PMID 37720118, 2023). "These factors encompass hyponatremia, sarcopenia and muscle mass, abnormal albuminuria and glomerular filtration rate, as well as the Urine Albumin-to-Creatinine Ratio." (PMID 37443036, 2023). "Conversely, the non-sarcopenia group had notably larger proportions of women and patients with CKD G3, and the BMI, DBP, and serum albumin levels in this group were higher than those in the sarcopenia group." (PMID 38068851, 2023). "The Cox proportional hazards model indicated albumin-bilirubin score and sarcopenia as independent prognostic factors (p < 0.01 each)." (PMID 38024081, 2023). "Our one-way analysis of variance suggested that serum albumin was markedly decreased in MHD patients with sarcopenia, and multivariate regression analysis indicated that NLR was an independent risk factor for the occurrence of sarcopenia." (PMID 36895911, 2023). "For PEM (serum albumin level ≤ 3.5 g/dL), Child–Pugh class B or C, or sarcopenia, nutritional intervention with divided meals (3 to 5 meals per day), LES, and BCAA-containing foods are provided." (PMID 36986091, 2023). "Sarcopenia (OR 5.58, 95% CI 1.70–18.29, p = 0.005) and preoperative albumin level (OR 0.81, 95% CI 0.69–0.95, p = 0.008) were also independently associated with neutropenia occurrence." (PMID 36814253, 2023). "Firstly, the presence of protein energy malnutrition with signs of sarcopenia and globular proteins disarrangement (i.e., through anthropometric measurements and blood albumin quantification, etc.)in CHF patients should be looked for and evaluated." (PMID 37242219, 2023). "Body mass index (BMI), nutritional risk screening (NRS) 2002 score, history of abdominal surgery, sarcopenia, and preoperative albumin were included in the multivariate logistic regression analysis." (PMID 35463676, 2022). "In univariate analysis, significant factors closely associated with RFS included serum albumin (p = 0.034), CEA levels (p = 0.011), number of liver metastases (p < 0.001), maximum diameter of the liver metastases (p = 0.002), sarcopenia status (p = 0.024)." (PMID 35619951, 2022). "Furthermore, in clinical practice, achieving normal albumin values (≥3.8 g/dL) due to adequate dietary intake and/or low inflammation may be limiting for the identification of certain classical risk factors such as muscle wasting or sarcopenia." (PMID 36145223, 2022).
sarcopenia (continued). "BMI (OR, 0.9; 95% CI, 0.8–0.99), body weight (OR, 0.9; 95% CI, 0.8–0.99), TG (OR, 0.5; 95% CI, 0.3–0.8), HGB (OR, 0.9; 95% CI, 0.9–0.99), and serum albumin (OR, 0.8; 95% CI, 0.7–0.9) were significant (p < 0.05) protective factors in sarcopenia in men." (PMID 36003303, 2022). "A good nutritional status, in particular an adequate protein intake reflected by normal albumin levels, and regular physical exercise are currently the most effective therapeutic measures to counteract sarcopenia." (PMID 35698920, 2022). "The mean value of BMI and serum albumin in the non-sarcopenia group was higher than in the sarcopenia group (P = 0.001; P = 0.007)." (PMID 35177018, 2022). "Among the hematological biomarkers identified as being correlated (negatively) with sarcopenia are albumin (Alb) and hemoglobin (Hb)." (PMID 36364963, 2022). "A similar experience was reported by Yu, who showed that patients with high fibrinogen–albumin ratios and incidence of sarcopenia, had shorter overall survival and recurrence-free survival than other patients." (PMID 35329856, 2022). "Our study demonstrated that sarcopenia, serum albumin < 40 g/L, N stage 2–3 and TNM stage III–IV are independently associated with poor OS in 213 ESCC patients who received RT or CRT in this analysis." (PMID 35501704, 2022). "On MVA, age ≥70 (p < 0.01), low albumin status (p = 0.03), and sarcopenia (p = 0.04) were identified as predictors of prolonged radiation treatment breaks." (PMID 35565223, 2022). "Nutritional indicators (sarcopenia, BMI, and serum albumin level) have been used to predict postoperative complications." (PMID 35909159, 2022). "Participants with sarcopenia had significantly lower free triiodothyronine, insulin, total protein, albumin, prealbumin, albumin/prealbumin ratio (A/G), alanine aminotransferase, triglycerides, and very low-density lipoprotein concentrations (P < 0.05)." (PMID 36419004, 2022). "BMI, NRS 2002 score, history of abdominal surgery, sarcopenia, and preoperative albumin were included in the multivariate logistic regression analysis." (PMID 35463676, 2022). "In the sarcopenia group, albumin levels and cardiopulmonary bypass time were the significant factors affecting hospital stay." (PMID 35313647, 2022). "Sarcopenia was correlated significantly with body mass index, albumin, female sex, resection style, mitotic index, rupture status, survival." (PMID 35177018, 2022). "Albumin levels and the interaction of sarcopenia and surgery were the independent factors influencing the short-term overall HRQOL after surgery." (PMID 36551629, 2022). "After adjusting for age, BMI, hemoglobin, albumin, calcium, phosphorus, CRP, AMC, protein, and MIS, multivariate analysis showed that the TyG index was positively associated with sarcopenia (OR 9.97; 95% CI, 2.90–34.23; p < 0.001)." (PMID 36191303, 2022). "After multivariate adjustment for potential confounders such as age, sex, BMI, glomerular filtration rate (GFR), albumin, and Charlson index, sarcopenia (defined with low HGS and low SMMI estimated by BIA) was an independent predictor of mortality." (PMID 34383112, 2022). "The results of our study showed that sarcopenia, together with albumin, TNM stage and N stage, were independent predictors for OS in ESCC patients who received RT or CRT." (PMID 35501704, 2022). "Albumin and total protein are considered good markers of nutritional status and were reported to be low in patients with sarcopenia." (PMID 35806895, 2022). "Accordingly, our results showed that age, low BMI, PDFF, albumin, and total cholesterol significantly contributed to sarcopenia in patients with CLD (p < 0.05 for all)." (PMID 35542962, 2022). "Next, our scoring system considered both tumor (number, size, AFP, major venous thrombosis), liver (albumin), and patient factors (sarcopenia) at the same time." (PMID 36248997, 2022).